CCT6B (chaperonin containing TCP1 subunit 6B)
Description:
Could function as a component of a tissue-specific chaperonin-containing T-complex (TRiC), a molecular chaperone complex that assists the folding of actin, tubulin and other proteins upon ATP hydrolysis.
Synonyms: TCP-1-zeta-2; Cctz2; TSA303; CCT-zeta-2; CCTZ-2
Tractability: PROTAC: ubiquitination databases record sites on it; its protein half-life has been measured.
Gene: Protein-coding gene on chromosome 17 (34,927,859 to 34,981,078, reverse strand). Ensembl gene ENSG00000132141.
Subcellular location: Cytoplasm
Subcellular location (Human Protein Atlas): Cytosol
Pathways (Reactome):
Metabolism of proteins: Association of TriC/CCT with target proteins during biosynthesis; Cooperation of PDCL (PhLP1) and TRiC/CCT in G-protein beta folding; Folding of actin by CCT/TriC; Formation of tubulin folding intermediates by CCT/TriC; Prefoldin mediated transfer of substrate to CCT/TriC
Gene Ontology:
Molecular function: protein binding; protein folding chaperone; ATP hydrolysis activity; ATP binding; ATP-dependent protein folding chaperone
Biological process: protein folding
Cellular component: chaperonin-containing T-complex; cytoplasm
Genetic constraint (gnomAD): Loss-of-function variants: 9 observed, 14.02 expected, observed/expected ratio (o/e) 0.64, 90% interval 0.39 to 1.12. The upper end of that interval is the gene's LOEUF score, 1.12, which puts it in group 4 of 6, group 1 being the genes least tolerant of losing a copy. Missense variants: 192 observed, 204.99 expected, observed/expected ratio (o/e) 0.94, 90% interval 0.83 to 1.06. Synonymous variants: 67 observed, 69.11 expected, observed/expected ratio (o/e) 0.97, 90% interval 0.8 to 1.19.
Homologues: Orthologues: chimpanzee CCT6B (97% identical), macaque CCT6B (97% identical), dog CCT6B (92% identical), pig CCT6B (92% identical), rabbit CCT6B (91% identical), guinea pig CCT6B (89% identical), zebrafish cct6a (84% identical), mouse Cct6b (83% identical), rat Cct6b (83% identical), tropical clawed frog cct6a (83% identical), Drosophila melanogaster CCT6 (68% identical), Caenorhabditis elegans cct-6 (65% identical). Paralogues in human: CCT6A (86% identical), CCT5 (30% identical), CCT4 (27% identical), CCT3 (27% identical), CCT7 (27% identical), TCP1 (27% identical), PIKFYVE (26% identical), CCT2 (25% identical), CCT8 (24% identical), CCT8L2 (22% identical), HSPD1 (21% identical), MKKS (18% identical), and 1 more.
Diseases named in the same sentence as CCT6B in open-access papers:
CCT6B is named in the same sentence as 13 diseases in open-access papers, as found by Europe PMC text mining. Sharing a sentence is not in itself a finding about the gene and the disease. The quoted sentences say what the papers report.
Burkitt lymphoma (2 papers, 2020 to 2021). A rare form of malignant mature B-cell non-Hodgkin lymphoma. "Further, a CCT6B gene mutation that may lead to TRiC loss-of-function was found in Burkitt lymphoma, and it was suggested that CCT6B may be a potential tumor suppressor gene." (PMID 34676169, 2021).
testicular cancer (2 papers, 2020 to 2021). A primary or metastatic malignant neoplasm that affects the testis. "In agreement, CCT6B high levels are specifically associated with testicular cancer, whereas high levels of CCT6A are associated with a broad range of cancers." (PMID 33846299, 2021). "Thus, it is possible that CCT6B overexpression in the non-seminomatous testicular cancer group may explain the higher invasiveness capacity of non-seminomatous TGCTs relative to seminomatous TGCTs." (PMID 32650378, 2020).
cholangiocarcinoma (1 paper, 2024). A carcinoma that arises from the intrahepatic biliary tree (intrahepatic cholangiocarcinoma) or from the junction, or adjacent to the junction, of the right and left hepatic ducts (hilar cholangiocarcinoma). "The expression of all 8 CCT members was increased in cholangiocarcinoma, colon adenocarcinoma, esophageal carcinoma, head and neck squamous cell carcinoma, liver hepatocellular carcinoma, LUAD, LUSC, prostate adenocarcinoma, rectum adenocarcinoma, and stomach adenocarcinoma, except for CCT6B." (PMID 39259093, 2024).
hepatocellular carcinoma (1 paper, 2020). A malignant tumor that arises from hepatocytes. "Moreover, a reduced synthesis of CCT6B mRNA was observed in hepatocellular carcinoma when compared to healthy tissue while the other components of TRiC complex were overexpressed." (PMID 32650378, 2020).
teratospermia (1 paper, 2021). "Together, these results indicated that Cct6b knockout can result in teratospermia characterized by neck bending and cytoplasmic redundancy." (PMID 34141486, 2021).
tumor (6 papers, 2021 to 2025). "We used the ONCOMINE database to compare the mRNA expression levels of the eight TRiC subunits in 20 different tumor types to corresponding normal tissues and found that all except CCT6B were significantly upregulated in multiple HCC datasets." (PMID 34676169, 2021). "The mRNA expression levels of TCP1, CCT2/3/4/5/6A/7/8 in HCC patients were lower in grade 1/2 than grade 3/4, while CCT6B expression decreased as the tumor grade increased." (PMID 34676169, 2021). "CCT6B was found to be involved in cell cycle regulation, promoting tumor cell proliferation." (PMID 41312091, 2025). "Our study showed that CCTs, except CCT6B, had higher expression levels in NSCLC tumor tissues, such as LUAD and LUSC." (PMID 39259093, 2024). "However, the expression levels of CCT6B were decreased in tumor tissues compared with non-tumor tissues in the two databases." (PMID 33897772, 2021).
cancer (3 papers, 2018 to 2024). A tumor composed of atypical neoplastic, often pleomorphic cells that invade other tissues. "Of notice, all the other TRiC genes except CCT6B were also among the most highly expressed in cancer and upregulated accordingly in the different subtypes, suggesting an important role of the TRiC complex specifically in BRCA as previously suggested." (PMID 29954368, 2018).
CCT6B also shares sentences with these, for which no sentence is quoted: colon adenocarcinoma (1 paper); esophageal carcinoma (1); head and neck squamous cell carcinoma (1); prostate adenocarcinoma (1); rectum adenocarcinoma (1); stomach adenocarcinoma (1).